SLC46A2 (solute carrier family 46 member 2)
Description:
Proton-coupled transporter that delivers pathogen-associated or danger-associated molecular patterns to cytosolic pattern recognition receptors as part of the innate immune response to microbes or tissue injury. Has selectivity toward muropeptides that contain the amino acid diaminopimelic acid (DAP-type peptidoglycan muropeptides) including Tri-DAP and tracheal toxin (TCT), common in Gram-negative bacteria and Gram-positive bacilli. In the context of immune recognition of skin microbiota, shuttles bacterial muropeptides across the endolysosomal membranes into the cytosol for recognition by NOD1, triggering MYD88-dependent secretion of IL1A and neutrophil recruitment in a pyroptosis-type inflammatory process. To a lesser extent and redundantly, transports muramyl dipeptides derived from most bacterial proteoglycans, eliciting NOD2 receptor activation and downstream inflammatory responses. Postulated to function as a dominant importer of cyclic GMP-AMP dinucleotides (cGAMPs) in monocyte and macrophage cell lineages. Selectively imports cGAMPs derived from pathogenic bacteria such as 3'3'-cGAMP thus providing for differential immune recognition of pathogenic versus commensal bacteria. During tumorigenesis may transport extracellular tumor-derived 2'3'-cGAMP across the plasma membrane of M1-polarized macrophages to activate the anti-tumoral stimulator of interferon genes (STING) pathway. The transport mechanism, its electrogenicity and stoichiometry remain to be elucidated (Probable).
Synonyms: TSCOT; Ly110
Tractability: Antibody: UniProt places it where antibodies can reach, with high confidence; its Gene Ontology location is reachable by antibodies, with high confidence; UniProt predicts a signal peptide or a membrane-spanning region.
Gene: Protein-coding gene on chromosome 9 (112,878,920 to 112,890,876, reverse strand). Ensembl gene ENSG00000119457.
Subcellular location: Endosome membrane; Cell membrane
Gene Ontology:
Molecular function: cyclic-GMP-AMP transmembrane transporter activity; symporter activity; transmembrane transporter activity
Biological process: cyclic-GMP-AMP transmembrane import across plasma membrane; positive regulation of nucleotide-binding oligomerization domain containing 1 signaling pathway; transmembrane transport
Cellular component: endosome membrane; plasma membrane; membrane; cell surface
Genetic constraint (gnomAD): Loss-of-function variants: 26 observed, 35.55 expected, observed/expected ratio (o/e) 0.73, 90% interval 0.54 to 1.01. The upper end of that interval is the gene's LOEUF score, 1.01, which puts it in group 4 of 6, group 1 being the genes least tolerant of losing a copy. Missense variants: 620 observed, 652.69 expected, observed/expected ratio (o/e) 0.95, 90% interval 0.89 to 1.01. Synonymous variants: 254 observed, 289.91 expected, observed/expected ratio (o/e) 0.88, 90% interval 0.79 to 0.97.
Homologues: Orthologues: chimpanzee SLC46A2 (99% identical), macaque SLC46A2 (97% identical), guinea pig SLC46A2 (85% identical), rabbit SLC46A2 (85% identical), dog SLC46A2 (83% identical), mouse Slc46a2 (77% identical), rat Slc46a2 (76% identical), pig SLC46A2 (76% identical), tropical clawed frog slc46a2 (44% identical), zebrafish slc46a2 (39% identical), Caenorhabditis elegans slc-46A (22% identical), Drosophila melanogaster CG42514 (21% identical), and 7 more. Paralogues in human: SLC46A3 (24% identical), SLC46A1 (21% identical).
Diseases named in the same sentence as SLC46A2 in open-access papers:
SLC46A2 is named in the same sentence as 7 diseases in open-access papers, as found by Europe PMC text mining. Sharing a sentence is not in itself a finding about the gene and the disease. The quoted sentences say what the papers report.
lung adenocarcinoma (1 paper, 2023). A carcinoma that arises from the lung and is characterized by the presence of malignant glandular epithelial cells. "Consistent with our study, previously published article also described SLC46A2 as a prognostic biomarker for lung squamous cell carcinomas and lung adenocarcinomas patients." (PMID 37185598, 2023).
lung squamous cell carcinomas (1 paper, 2023). "In addition, SLC46A2, ZNF367, AC107214.1 and NCBP1 genes were identified as survival-related genes of patients with lung squamous cell carcinoma." (PMID 37185598, 2023).
psoriasis (1 paper, 2023). An autoimmune condition characterized by red, well-delineated plaques with silvery scales that are usually on the extensor surfaces and scalp. "Methotrexate is also a commonly used therapeutic agent in psoriasis; its anti-psoriasis mechanism is complex and includes inhibitory effects on folate-dependent enzyme, NF-κB, lincRNA-p21, NO synthase, and solute-carrier family 46 member 2 (SLC46A2)." (PMID 37762693, 2023).
vitiligo (1 paper, 2024). Generalized well circumscribed patches of leukoderma that are generally distributed over symmetric body locations and is due to autoimmune destruction of melanocytes. "Regarding ECA25, six significant genomic regions were identified, although genes related to biological processes associated with vitiligo (TXN, LPAR1, SLC46A2, PRPF4, TRIM32, STOM, BRINP1, and DAB2IP) were only found in five of them." (PMID 39199954, 2024).
tumor (3 papers, 2019 to 2023). "Mainly, survival analyses showed that the same expression of SLC46A2, ZNF367, AC107214.1 and NCBP1 genes in the primary and LNM lesions can provides more potent prognostic information when no analyses of the primary tumor have been done." (PMID 37185598, 2023).
SLC46A2 also shares sentences with these, for which no sentence is quoted: cancer (1 paper); lung carcinoma (1).